MS4A4E (membrane spanning 4-domains A4E)
Tractability: Antibody: UniProt predicts a signal peptide or a membrane-spanning region.
Gene: Protein-coding gene on chromosome 11 (60,200,270 to 60,243,137, reverse strand). Ensembl gene ENSG00000214787.
Subcellular location: Membrane
Gene Ontology:
Cellular component: membrane
Genetic constraint (gnomAD): Loss-of-function variants: 5 observed, 4.5 expected, observed/expected ratio (o/e) 1.11, 90% interval 0.56 to 1.86. That is too few expected variants to judge how well the gene tolerates losing a copy. Missense variants: 62 observed, 57.73 expected, observed/expected ratio (o/e) 1.07, 90% interval 0.87 to 1.33. Synonymous variants: 19 observed, 20.68 expected, observed/expected ratio (o/e) 0.92, 90% interval 0.64 to 1.35.
Homologues: Orthologues: mouse Ms4a4a (27% identical), rat Ms4a4a (26% identical). Paralogues in human: MS4A4A (38% identical), MS4A8 (14% identical), MS4A15 (14% identical), MS4A12 (14% identical), MS4A18 (13% identical), MS4A2 (13% identical), MS4A1 (12% identical), MS4A6A (12% identical), MS4A7 (12% identical), MS4A14 (11% identical), MS4A3 (11% identical), MS4A5 (10% identical), and 4 more.
Diseases named in the same sentence as MS4A4E in open-access papers:
MS4A4E is named in the same sentence as 4 diseases in open-access papers, as found by Europe PMC text mining. Sharing a sentence is not in itself a finding about the gene and the disease. The quoted sentences say what the papers report.
Alzheimer disease (2 papers, 2017 to 2023). A progressive, neurodegenerative disease characterized by loss of function and death of nerve cells in several areas of the brain leading to loss of cognitive function such as memory and language. "The best host gene signature MS4A4E that encodes protein Membrane Spanning 4-Domains A4E, which may be related with Alzheimer’s disease." (PMID 37332019, 2023). "And interestingly, the best host gene signature MS4A4E that encodes protein Membrane Spanning 4-Domains A4E, which may be related with Alzheimer’s disease." (PMID 37332019, 2023).
glioma (1 paper, 2022). A benign or malignant brain and spinal cord tumor that arises from glial cells (astrocytes, oligodendrocytes, ependymal cells). "In conclusion, MS4A4A, MS4A4E, MS4A6A, MS4A7, TMEM176A, and TMEM176B may act as potential diagnostic or prognostic biomarkers in glioma and play a role in forming the immune microenvironment in gliomas." (PMID 35734424, 2022). "In TCGA data, the expression level of MS4A4A, MS4A4E, MS4A6A, MS4A7, TMEM176A, and TMEM176B in IDH wild-type glioma was elevated." (PMID 35734424, 2022). "Using bioinformatics analysis methods based on the data from public databases, we found that the expression of MS4A4A, MS4A4E, MS4A6A, MS4A7, TMEM176A, and TMEM176B was significantly overexpressed in glioma tissues compared with that of normal tissues." (PMID 35734424, 2022). "Therefore, these preliminary results indicate that MS4A4A, MS4A4E, MS4A6A, MS4A7, TMEM176A, and TMEM176B are potential prognostic factors for glioma." (PMID 35734424, 2022). "In TCGA data, the expression level of MS4A4A, MS4A4E, MS4A6A, MS4A7, TMEM176A, and TMEM176B in 1p/19q non-codel glioma was elevated." (PMID 35734424, 2022).
tumor (1 paper, 2022). "According to the tumor grades, in TCGA database, compared with WHO II and III, the transcription levels of MS4A4A, MS4A4E, MS4A6A, MS4A7, TMEM176A, and TMEM176B were the highest in WHO IV." (PMID 35734424, 2022).
MS4A4E also shares sentences with these, for which no sentence is quoted: cancer (1 paper).